RNU4ATAC2P (RNA, U4atac small nuclear 2, pseudogene)
Gene: Small nuclear RNA gene on chromosome 5 (159,318,042 to 159,318,167, forward strand). Ensembl gene ENSG00000221601.
Homologues: Orthologues: chimpanzee RNU4ATAC2P (100% identical), macaque RNU4ATAC2P (97% identical). Paralogues in human: RNU4ATAC16P (87% identical), RNU4ATAC18P (82% identical), RNU4ATAC11P (79% identical).